BCL2 (BCL2 apoptosis regulator)
Diseases named in the same sentence as BCL2 in open-access papers (continued):
Sharing a sentence is not in itself a finding about the gene and the disease.
glioblastoma (continued). "By dissecting ZIKV action on GSCs, we provide an alternative tool for glioblastoma treatment, and demonstrate that mir34c can inhibit GSCs, such as ZIKV, by reducing Bcl2 that could potentially increase the effect of chemo/radiotherapies." (PMID 30890698, 2019). "Moreover, we observed that Zika infection reduces Bcl2 expression, which can be responsible for the apoptotic response, together with the reduction of NUMB, decreasing AKT phosphorylation in glioblastoma cell lines." (PMID 30890698, 2019). "The XPO1 inhibitor leptomycin B (LMB) and KPT-330 consistently downregulated Mcl-1 but not Bcl-2 or Bcl-xL in a dose-dependent manner in U87 and U251 glioblastoma cells and H1299 NSCLC cells." (PMID 31113936, 2019). "Glioblastoma cells treated with the compound-1H led to an elevation of apoptosis-related proteins (Bax, cleaved caspase-3, cleaved caspase-9 and cleaved PARP), while Bcl-2 was down-regulated in a dose-dependent manner." (PMID 29988358, 2018). "Expression of Bcl-2 was reduced in T98G and LN229 glioblastoma cells." (PMID 27172899, 2016). "In the T98G glioblastoma multiforme cell line, the expression of AKT3 or PI3KCA genes is downregulated by siRNAs that target their mRNAs and this leads to the upregulation of the BAX/BCL-2 mRNA expression ratio." (PMID 24967401, 2014). "Zn-curc was detected in the glioblastoma tissues, highlighting its capacity to reach the tumor site and affect molecular pathways important for tumor angiogenesis, and impairment of response to therapies such as VEGF, MDR1 and Bcl2." (PMID 24220325, 2013). "Saponin 1 treatment significantly induced Bax expression and inhibited Bcl-2 expression in both glioblastoma cell lines (38.5 ± 4.8% and 27.1 ± 2.5% in U251MG and U87MG cells, respectively), resulting in a decreased Bcl-2/Bax ratio when compared with the vehicle controls." (PMID 24278406, 2013). "Furthermore, tetrandrine exhibits pro-apoptotic activity in various glioblastoma cell lines (U87, U251, and GBM 8401/luc2) by increasing the active forms of caspase-3, -8, and -9, upregulating Bax, inducing PARP cleavage, and downregulating Bcl-2." (PMID 40286187, 2025). "Treatment of glioblastoma cells with MA led to the inhibition of GSK3 kinase, resulting in the downregulation of SRSF1/5, PTPB1, and hnRNP with decreased levels of anti-apoptotic genes such as BCL2, BCL-xL, Survivin, MCL1, and BMI1 while increased in Anxa7, a tumor suppressor gene." (PMID 39863145, 2025). "Thus, the reduction of Bcl2 and NUMB decreases AKT phosphorylation and increases the apoptotic response in glioblastoma cell lines, highlighting the importance of ZIKV as a potential oncolytic therapy for glioblastoma treatment." (PMID 39347716, 2024). "Similarly, MSC-TRAIL combined with an AMPK inhibitor enhanced killing of glioblastoma cells by increasing expression of the pro-apoptotic BCL-2 family protein Bax and simultaneously reducing the expression of the anti-apoptotic proteins FLIP, XIAP and BCL-2." (PMID 36496977, 2022). "In human SHG44 glioblastoma cells, the RES/temozolomide combination has revealed additional antiproliferative effects upon inhibition of mTOR signaling and downregulation of the antiapoptotic Bcl-2 protein and increase in ROS production, and subsequent activation of AMPK." (PMID 35328780, 2022). "It has been reported that the low rate of apoptosis in some cancer cells, including glioblastoma, ovarian cancer, CML and AML, may be contributed to downregulation of miR-153 which targets three antiapoptotic genes, Bcl-2, Mcl-1 and XIAP through binding to 3 ́UTR of their mRNAs." (PMID 36158686, 2022). "This triterpene has shown anti-cancer potential by inducing apoptosis and suppressing cancer cell proliferation and modulating apoptosis regulators such as glioblastoma multiforme (GBM), B-cell CLL/lymphoma 2 (BCL-2), and caspases." (PMID 34885816, 2021).
glioblastoma (continued). "Similarly, treating human U-118MG glioblastoma cells with the cytotoxic Bn analogue AN-215 reduced tumor size by 50%, decreased tumoral VEGF levels by 45%, and decreased the relative ratio of Bcl-2 to Bax proteins by 90%, indicating a net apoptotic gain and showing the effectiveness of the therapy." (PMID 34539578, 2021). "Studies in human glioblastoma multiforme (GBM) cells identified that PKM2 under oxidative stress translocates to the mitochondria, where it phosphorylates BCL-2 at threonine 69 to prevent its ubiquitination by E3 ligase and its subsequent degradation." (PMID 33503959, 2021). "In summary, our finding showing that CFTR regulates Akt/Bcl2‐mediated anti‐apoptotic pathway, warrants future investigations into the potential of using CFTR as a therapeutic target and exploring combination therapy to target PI3K/Akt pathway in the treatment of glioblastomas." (PMID 32463592, 2020). "Treatment with a Bcl2 inhibitor does not fully explain the effect of gossypol on glioblastoma." (PMID 31658771, 2019). "Inhibitors of Bcl-xL rather than Bcl-2 enhances KPNB1 inhibitor-induced apoptosis in glioblastoma cells, suggesting that combination of Bcl-xL inhibitors and KPNB1 inhibitors, such as IPZ and INI-43, may be efficacious and safe for solid tumors therapy." (PMID 29520102, 2018). "The levels of pro-apoptotic Bax and cleaved caspase-3 were enhanced, and Bcl-2 expression was downregulated from leucine-rich α2 glycoprotein 1 (LRG1)-silencing, which inhibited the growth of xenograft tumors and induced apoptosis of U251 glioblastoma cells in vitro and in vivo." (PMID 30201893, 2018). "To test our hypothesis that combined treatment with the Bcl-2 inhibitor ABT263 and the Mcl-1 inhibitor GX15-070 yields a more favorable antineoplastic activity in glioblastoma when compared to single-agent treatments, we first examined effects on cellular proliferation by MTT assays." (PMID 26008975, 2015). "Prior work in a small number of cell culture models suggests glioblastoma (GBM) cells may have survival dependencies on the apoptotic blocks BCL-XL, BCL-2 and/or MCL-128–30." (PMID 39572533, 2024). "Similarly, Karlovic and colleagues (2007) found that LiCl treatments (20 mmol/L) in A1235 glioblastoma cells altered the levels of proteins such as Bcl-2 and proCAS-3, and there was no cleavage of PARP1, reinforcing with our work that lithium does not affect this pathway." (PMID 39339471, 2024). "Similarly, while early senescent glioblastoma cells were killed by selective BCL-2 inhibition—although no proliferating control cells were included in the assay, late senescent glioblastoma cells were insensitive to BCL-2 inhibition and depended solely on BCL-xL for their survival." (PMID 36128715, 2022). "We also verified by western blot analysis that the antiapoptotic protein Bcl-2 and total caspase-9 levels were decreased, while those of proapoptotic Bax and cleaved caspase-9 were increased by drug treatment, demonstrating that CYT387 could promote glioblastoma cell apoptosis." (PMID 34544426, 2021). "Therefore, the effect of ATF5 knockdown can be highly cell type-dependent and could therefore explain why BCL2 seems to be regulated by ATF5 in some glioblastoma cell lines but not in others." (PMID 29137451, 2017). "In order to examine whether TIC10/ONC201 along with inhibition of Bcl-2/Bcl-xL results in a mutually enhanced anti-proliferative effect, we performed MTT assays in pediatric (SF188), adult (T98G) and proneural (MGPP-3 - derived from a transgenic mouse model) glioblastoma cells." (PMID 26474387, 2015). "MiR-451 was found to directly impact glioblastoma cell proliferation, invasion, and apoptosis by down regulating the expression of Akt1, CyclinD1, MMP-2, MMP-9 and B-Cell CLL/lymphoma 2 (Bcl-2), however, no direct interaction of any of these mRNAs were found." (PMID 24670365, 2014).
glioblastoma (continued). "Interestingly, the deletion of the H3K27ac-preferred SE regions of BCL2 and ZBTB7B neither reduced the expression of their target genes nor the glioblastoma stem-like properties." (PMID 37759202, 2023).
osteosarcoma (192 papers, 2008 to 2026). A usually aggressive malignant bone-forming mesenchymal neoplasm, predominantly affecting adolescents and young adults. "In a three-dimensional osteosarcoma model, the increased expression of several drug-resistance-related genes (Bcl2, Abcb1, Abcg2, Nanog, Sox2) was closely associated with heightened glutamine metabolism." (PMID 41300631, 2025). "Other herbal extracts or phytochemicals, such as curcumin, resveratrol, and green tea polyphenols, have been shown in studies to reduce Bcl2 expression and cause apoptosis in multiple types of cancer cells, such as osteosarcoma." (PMID 38738026, 2024). "Polydatin inhibition of the Wnt/β-catenin pathway in human osteosarcoma cells has been linked to a reduction in the Bax/Bcl-2 ratio, contributing to apoptotic death." (PMID 38132944, 2023). "In osteosarcomas, overexpression of Bcl-2 and Bcl-xL has been reported to be associated with poor prognosis." (PMID 35337159, 2022). "In osteosarcoma, we previously reported that anti-apoptotic Bcl-2 was directly targeted by miR-143, and miR-143 is downregulated in osteosarcoma and causes the upregulation of anti-apoptotic Bcl-2." (PMID 28977896, 2017). "The B-cell lymphoma 2 (BCL2) family proteins are suspected to regulate apoptotic cell death caused by chemotherapeutic agents in human osteosarcoma cells." (PMID 27356624, 2016). "In the osteosarcoma model, isovitexin further induced apoptosis and caused epigenetic regulation through the DNA methyltransferase 1 (DNMT1)/miR-34a/Bcl-2 axis, causing the suppression of stemness and inducing apoptosis in the spheres derived from osteosarcoma cells." (PMID 32708138, 2020). "In a recent report, the researchers demonstrated that miR-143 could inhibit the expression of Bcl-2 and cause caspase-3 activation, thus inducing apoptosis in osteosarcoma cells." (PMID 28134320, 2017). "Thus, survivin served as a target for the regulation of evodiamine-induced apoptosis in osteosarcoma, and was associated with Bcl-2, Bax and caspase-3 expression levels." (PMID 25621054, 2015). "Similarly, the sensitivity to cisplatin was increased by celecoxib in a human osteosarcoma cell line (MG-63) and this effect was linked to a down-regulation of anti-apoptotic proteins survivin, Bcl-2, and an inhibition of the survival pathway PI3K/Akt." (PMID 20339581, 2010). "For instance, in NSCLC cell lines and osteosarcoma cells, the overexpression of miR-506 significantly increases the sensitivity of cancer cells to apoptosis, which is closely associated with the upregulation of Bax and the downregulation of Bcl-2 at both the mRNA and protein levels." (PMID 40248198, 2025). "Here, we focus on evaluating the GO as a carrier of bcl-2 siRNA in osteosarcoma cell lines and assessing its bioactivity, and the inflammatory response of GO in non-tumour models in vivo." (PMID 41998059, 2026). "This is achieved through regulation of the VEGFR2/STAT3/Bcl-2 signal pathway in both in vivo and in vitro studies of osteosarcoma." (PMID 41438689, 2026). "For instance, the application of the compounds diosmetin and 6-gingerol to osteosarcoma cells has been reported to suppress Bcl-2 and augment Bax expression and, therefore, induce apoptosis." (PMID 40283955, 2025). "Ginsenoside Rh2 can affect the expression of apoptotic proteins such as Bcl-2 in osteosarcoma (U-2 OS) and esophageal cancer (ECA109 and TE-13) cells, thereby inhibiting tumor progression." (PMID 40490812, 2025). "In anaplastic thyroid carcinoma and osteosarcoma, high SIGLEC-15 expression likewise predicted worse outcomes and was linked to the activation of pro-tumor pathways (STAT3/BCL-2)." (PMID 40943560, 2025). "The antiapoptotic function of WT1 is not limited to fibroblasts in pulmonary fibrosis, as high WT1 expression in osteosarcoma has been shown to promote BCL2 levels and resistance to apoptosis." (PMID 40493404, 2025).
osteosarcoma (continued). "A crucial mechanism supporting its tumor-suppressive impact is its potential to regulate apoptosis through the direct targeting of BCL-2, a prominent anti-apoptotic protein commonly overexpressed in Osteosarcoma." (PMID 40429954, 2025). "This study aimed to investigate the effects of Hes and cisplatin (Cis) on the Bax/Bcl-2 apoptotic pathway in osteosarcoma cells." (PMID 40572648, 2025). "TNF-α, in particular, is a potent NF-κB activator and has been demonstrated to protect osteosarcoma cells from apoptosis by enhancing the expression of anti-apoptotic proteins like Bcl-2 and cIAPs." (PMID 39949765, 2025). "This is consistent with earlier studies where ouabain upregulated the expression of BAX and decreased the expression of BCL-2 in rats and in human osteosarcoma cells." (PMID 41354896, 2025). "When exposed to chemotherapy-induced stress, NF-κB is activated and stimulates the transcription of anti-apoptotic genes like Bcl-2 and Bcl-xL, which protect osteosarcoma cells from apoptosis." (PMID 39949765, 2025). "By lowering BCL-2 expression, miR-143 restores apoptotic pathways, sensitizing Osteosarcoma cells to programmed cell death." (PMID 40429954, 2025). "This suggests that circUBAP2 promotes cell survival by enhancing Bcl-2 levels, thereby preventing apoptosis in osteosarcoma cells." (PMID 40283955, 2025). "Alterations in the expression of apoptosis-related proteins Bcl-2 and Bax also confirmed that PA promoted apoptosis in osteosarcoma cells." (PMID 40991530, 2025). "For example, hsa_circ_0001846, generated by the circularization of exons 11 to 14 of UBAP2 pre-mRNA, has been shown to sequester miR-143, thereby up-regulating Bcl-2 and promoting osteosarcoma progression." (PMID 41194937, 2025). "Additional predicted targets of miR-30a and miR-30e within this pathway include PIK3CA, mTOR, FOXO3, MMP13, SOX9, BCL2, VEGFA, and CCND1, all of which have been previously associated with osteosarcoma pathogenesis." (PMID 40862758, 2025). "It suppresses tumor angiogenesis and induces autophagy and apoptosis in osteosarcoma cells by inhibiting the downstream VEGFR2/STAT3/BCL-2 signaling pathway." (PMID 41395622, 2025). "For example, NF-κB regulates the production of anti-apoptotic proteins such as Bcl-2 and Bcl-xL, which facilitate osteosarcoma cell’s evasion of chemotherapy-induced apoptosis." (PMID 39949765, 2025). "The expression levels of apoptosis-related genes (Bax, Bcl-2, Caspase-3, and Survivin) in osteosarcoma (U2OS) cells were analyzed by comparing the Hes- and Cis-treated groups to the control group." (PMID 40572648, 2025). "It decreased MMP levels, triggered apoptosis by increasing Bax expression and Caspase-3 activity, and decreased Bcl-2 expression, thereby exerting an anti-osteosarcoma effect." (PMID 38297292, 2024). "Paclitaxel has been shown to induce apoptosis by promoting the cleavage of caspase-3 and -9 cleavage and decreasing BCL2 expression in human osteogenic sarcoma cells." (PMID 39770941, 2024). "In 2022, the anti-cancer effective synergism between PL and DXN was shown against osteosarcoma cells via the downregulation of the Bcl2 gene." (PMID 38253759, 2024). "Among the five DE-ERSRGs, the Kaplan–Meier survival analysis suggested that osteosarcoma patients exhibiting high expression levels of BCL2, MAGEA3, MAP3K5, and TXNDC12 had significantly improved overall survival rates." (PMID 38229155, 2024). "We demonstrated that Vitex increased the active form of caspase-3, decreased levels of Bcl-2 and survivin proteins, and increased Bax protein levels in human osteosarcoma cells." (PMID 38612399, 2024). "OA treatment induced apoptosis in osteosarcoma cells, a process regulated by Bcl-2 and caspase-3 through inhibition of the Notch signaling pathway." (PMID 38668524, 2024).
osteosarcoma (continued). "MCL-1 expression has also been associated with resistance to agents targeting BCL-2 and/or BCL-xL, however the osteosarcoma cells survived dual ABT-199/A-1331852 exposure regardless of their MCL-1 expression levels." (PMID 39497108, 2024). "A study from 2010 showed that miR-143 was downregulated in osteosarcoma cell lines and tumor samples, and its levels of restoration allowed a direct targeting of Bcl-2, reducing cell viability and promoting apoptosis." (PMID 37720343, 2023). "We already demonstrated the therapeutic potential of specifically targeting Bcl-xL and Bcl-2 on chondrosarcoma and osteosarcoma cells." (PMID 37719019, 2023). "In contrast, the anti-apoptotic gene BCL2 and metallothionein family (MT 1G and 1L) were upregulated in high-grade osteosarcoma according to work using different genetic analysis methodologies." (PMID 37107591, 2023). "In this study, PIP significantly reduced the Bcl-2 protein expression level in both osteosarcoma cell lines." (PMID 36895009, 2023). "In summary, miR-4270 mainly decreased the expression of the anti-apoptotic proteins Bcl-xL and Mcl-1, whereas miR-342-5p mainly decreased that of Bcl-xL and also Bcl-2 in osteosarcoma cells." (PMID 37719019, 2023). "Activated by CERB3, c-Jun upregulates MMP9 and Bcl-2 to promote osteosarcoma proliferation and metastasis." (PMID 37197432, 2023). "This shows that SIGLEC-15 inhibits tumor proliferation by affecting the activity of the STAT3/Bcl-2 signaling pathway, thereby affecting the apoptosis and pyroptosis of osteosarcoma cells." (PMID 36358792, 2022). "MiR-342-5p decreased Bcl-2 protein expression (from 1.4 to 2-fold) in the three osteosarcoma cell lines." (PMID 35337159, 2022). "We observed that Cd44-positive osteosarcoma cells expressed significantly higher levels of Bcl2 mRNA, compared to Cd44-negative osteosarcoma cells, consistent with the pro-survival function of CD44." (PMID 35955749, 2022). "The antiapoptotic protein Bcl-2, mainly located in the outer membrane of the mitochondria, was upregulated in osteosarcoma to inhibit the apoptosis induced by various stimuli, injury, and cell survival signals." (PMID 35694235, 2022). "Recent studies have highlighted TYK2 can act as an oncogene, with TYK2 activation increasing STAT1 phosphorylation and the expression of BCL-2 in T-cell acute lymphoblastic Leukemia and osteosarcoma." (PMID 35152270, 2022). "Knockdown of endogenous Bcl-2 significantly reduces hypoxia-induced cell invasion and migration in human osteosarcoma." (PMID 34980181, 2022). "In osteosarcoma cells, lncPVT1 regulates BCL2 through miR-195; when lncPVT1 is upregulated, the miR-195 level decreases and BCL2 transcript increases, resulting in inhibition of apoptosis." (PMID 34754096, 2022). "KIF21B decreasing expression facilitated cell apoptosis and impeded cell growth and tumorigenesis in nude mice through the inhibition of PI3K/AKT pathway and decreasing of Bcl-2 and increasing of Bax expression in osteosarcoma." (PMID 36451772, 2022). "Our previous in vitro studies found that tanshinone IIA inhibited cell proliferation and promoted apoptosis by regulating the expression level of Bcl-2/Bax in osteosarcoma cells." (PMID 34422073, 2021). "In this study, the expression levels of activated caspase-3, caspase-7, caspase-9, cleaved PARP, Bcl-2 and Bcl-xl were detected by Western blotting to study the mechanism by which aloin promotes osteosarcoma apoptosis." (PMID 34819120, 2021). "For example, miR‐125b down‐regulates Bcl‐2 in osteosarcoma, thereby sensitizing osteosarcoma cells to cisplastin treatment." (PMID 33332677, 2021). "The results showed that BCL-2 was localized in the cytoplasm and its expression was decreased in osteosarcoma treated with anti-T." (PMID 34565443, 2021). "On the other hand, the inhibition of endoplasmic reticulum stress accompanied by the increase of Bcl-2 lead to the inhibition of osteosarcoma cell apoptosis." (PMID 34646824, 2021).